CATSPERE (catsper channel auxiliary subunit epsilon)
Description:
Auxiliary component of the CatSper complex, a complex involved in sperm cell hyperactivation. Sperm cell hyperactivation is needed for sperm motility which is essential late in the preparation of sperm for fertilization.
Synonyms: C1orf101; MGC33370; C10orf101
Tractability: Antibody: UniProt predicts a signal peptide or a membrane-spanning region; its Gene Ontology location is reachable by antibodies, with medium confidence.
Gene: Protein-coding gene on chromosome 1 (244,454,377 to 244,641,177, forward strand). Ensembl gene ENSG00000179397.
Subcellular location: Cell projection, cilium, flagellum membrane
Subcellular location (Human Protein Atlas): End piece; Mid piece; Principal piece; Annulus
Gene Ontology:
Biological process: flagellated sperm motility; sperm capacitation; spermatogenesis
Cellular component: sperm end piece; sperm midpiece; sperm principal piece; CatSper complex
Genetic constraint (gnomAD): Loss-of-function variants: 40 observed, 58.25 expected, observed/expected ratio (o/e) 0.69, 90% interval 0.53 to 0.89. The upper end of that interval is the gene's LOEUF score, 0.89, which puts it in group 3 of 6, group 1 being the genes least tolerant of losing a copy. Missense variants: 672 observed, 777.2 expected, observed/expected ratio (o/e) 0.86, 90% interval 0.81 to 0.92. Synonymous variants: 240 observed, 277.42 expected, observed/expected ratio (o/e) 0.87, 90% interval 0.78 to 0.96.
Homologues: Orthologues: chimpanzee CATSPERE (98% identical), macaque CATSPERE (87% identical), dog CATSPERE (67% identical), rabbit CATSPERE (66% identical), pig CATSPERE (58% identical), mouse Catspere2 (53% identical), mouse Catspere1 (52% identical), rat Catspere (49% identical).
Diseases named in the same sentence as CATSPERE in open-access papers:
CATSPERE is named in the same sentence as 3 diseases in open-access papers, as found by Europe PMC text mining. Sharing a sentence is not in itself a finding about the gene and the disease.
CATSPERE shares sentences with these, for which no sentence is quoted: colorectal cancer (1 paper); esophageal squamous cell carcinoma (1); gastric cancer (1).